IL4 (interleukin 4)
Diseases named in the same sentence as IL4 in open-access papers (continued):
Sharing a sentence is not in itself a finding about the gene and the disease.
asthma (continued). "Depletion of T cells in sensitized mice inhibits asthma pathology including eosinophil recruitment to the lungs, and the absence of eosinophils decreases IL-4, IL-5 and IL-13 production, and also impairs T cell recruitment/accumulation of effector T cells to the lungs." (PMID 27203689, 2016). "Interestingly, these differences clustered in genes highly associated with asthma (ORMDL family) and IgE regulation (RAD50, IL13, and IL4), but not in T-regulatory genes (FOXP3, RUNX3)." (PMID 27510897, 2016). "However, blocking Th2 cytokines such as IL-4, IL-5, and IL-13 despite not been completely explored has shown some promising results in selected patients with asthma." (PMID 26334389, 2016). "The pathogenesis of asthma is directed by allergen-specific Th2 cells generated in the secondary lymphoid organs such as the BLN, and the migration of Th2 cells into lung plays an important role in mobilization of eosinophils via the secretion of IL-4 and IL-5." (PMID 26488300, 2015). "So far, asthma therapy uses drugs which alleviate the symptoms but do not inhibit the mechanism responsible for the expression of inflammatory mediators such as the cytokines interleukin-4 (IL-4), interleukin-13 (IL-13) and interleukin-5 (IL-5)." (PMID 26117852, 2015). "We found that the deficiency in Gpr97 did not affect the altering obviously in Th2-related cytokines, including IL-4 and IL-6, and the significant decrease in the Th1-related cytokine IFN-γ, suggesting that Gpr97 is not essential for T cell proliferation and differentiation in asthma." (PMID 26132811, 2015). "IL-4 was increased in patients with both atopic and nonatopic asthma." (PMID 26101464, 2015). "In addition to Th2 cells that produce IL-4, IL-5, and IL-13, double IL-4- and IL-17-expressing memory CD4+ T cells were detected in severe asthmatic patients and in lungs of mice developing experimental asthma." (PMID 26284078, 2015). "In addition, activating the receptor by transgenic expression or direct administration of IL-4 or IL-13 into the lungs in the absence of lymphocytes elicited symptoms of asthma including eosinophilia, mucus production, and AHR." (PMID 22292924, 2012). "To date, this SNP has shown associations with inflammatory and autoimmune diseases such as arthritis rheumatoid, asthma, allergic diseases and atopy, but the entire role in CKD of IL-4 and its signalling pathway through IL4R still remains unknown and further studies are needed." (PMID 22817530, 2012). "The Th2 cytokines IL-4 and IL-13 also seem to play a role in asthmatic inflammation, but therapies targeting IL-5, IL-4, or IL-13 have provided little or no relief of asthma symptoms and little relief from airways hyperresponsiveness." (PMID 23150736, 2012). "Besides inhibition of eotaxin-1 and MCP expression by simvastatin, neither IL-13 nor simvastatin treatment changed the expression of other asthma-relevant Th2-type cytokines such as IL-4, CCL5 (RANTES), CCR3, or IL-5Ra." (PMID 22583375, 2012). "However, in PBMCs from asthma patients the increase in IFNγ correlated significantly with IL-2 (ρ = 0.648 p<0.05), but not with IL4 or IL-13, showing a Th1 dominant shift in response to sitostanol." (PMID 23091602, 2012). "Moreover, some reports suggested that an increased IL-4 cytokine response is not necessarily a reflection of asthma activity but rather of the atopic state per se." (PMID 21197090, 2010). "Other biologic agents targeting IL-5, and IL-4/IL-13 did not demonstrate any serious or severe treatment-related adverse events in asthma patients, There has been some conflicting information on the safety of TNF-alpha blocking agents in the treatment of asthma." (PMID 20016776, 2009). "In a mouse asthma model, BALB/c mice treated with imiquimod cream containing siNPRA chitosan nanoparticles showed significantly reduced airway hyperresponsiveness, eosinophilia, lung histopathology and pro-inflammatory cytokines IL-4 and IL-5 in lung homogenates compared to controls." (PMID 18279512, 2008).
asthma (continued). "Thus among asthma patients, those who had positive anti-Hsp60 and anti-Hsp70 were more likely to report a family history of asthma and had higher levels of IgE and IL-4 than those without such antibodies." (PMID 15710045, 2005). "However, the etiologic link between anti-Hsps and asthma (its severity and related inflammatory responses such as interleukin-4 and immunoglobulin E) has not been established." (PMID 15710045, 2005). "The two forms of asthma phenotypes are type 2-low, characterized by non-eosinophilic inflammation, neutrophilic involvement, metabolic responses, and type 2-high IL-5 and IL-13, which are primarily eosinophilic and pathologically driven by Th2 cells that produce IL-4." (PMID 39594470, 2024). "Our finding of interleukin production as a top PBMC asthma module is not surprising, given the broad representation of this module and the pervasive roles that interleukins play in orchestrating inflammatory processes in asthma, including IL-4, IL-5, and IL-13 in type 2 inflammation." (PMID 37730635, 2023). "Since individuals with asthma and allergic diseases, which are not commonly encountered comorbidities in COVID-19, experience overactivation of type 2 immune response, including IL4, it is also proposed that the overexpression of this protein might play a protective role against COVID-19 infection." (PMID 37795240, 2023). "The animal experiments verified that Danlong Dingchuan Decoction could effectively reduce IL-4, IL-6, IL-8, and IL-1β expression in the lung tissue of asthmatic mice, decrease TLR4 mRNA expression, and inhibit Th2 cytokine-mediated inflammatory response to treat asthma." (PMID 35186104, 2022). "Here, we report a case of severe asthma with refractory ECRS and EOM in which total control of these allergic diseases could not be achieved with a single biologic but could be achieved via the sequential use of the anti-IL-5 receptor antibody and human anti-IL-4/13 receptor monoclonal antibody." (PMID 35454111, 2022). "However, IL-4 and IL-25 were similar in asthma patients with or without comorbid AR." (PMID 35348596, 2022). "Some scholars found that in an OVA-induced mouse asthma model, Que could regulate the expression of the T-bet and GATA-3 genes and affect the production of Th1/Th2 cytokines, resulting in a decrease in the IL-4 level of Th2 cytokines and an increase in the IFN-γ level of Th1 cytokines." (PMID 34838003, 2021). "As basophils and mast cells can produce β-HEX, IL-4 and IL-5 after allergen stimulation, and secreted enzymes such as tryptase can induce the release of β-HEX from eosinophils in the blood, these molecules may engage in both the induction and exacerbation of asthma through positive feedback loops." (PMID 33036262, 2020). "Although no study was available before for the association IL‐4 polymorphism with steroid‐induced ONFH, this SNP has been associated with autoimmune hepatitis, osteoarthritis, asthma, chronic periodontitis (Chen, Zhang, & Wang, 2016), and other clinical features." (PMID 30697966, 2019). "Therefore, biologics targeting IL-4/IL-13 may be useful in patients with proof of T2-high asthma based on the presence of type 2 inflammation regardless of their baseline blood eosinophil levels." (PMID 30050954, 2018). "Adhesion assays with eosinophil reveal that IL-4 increases VCAM-1 expression in airway endothelial cells and results in the increased adhesion of eosinophils to VCAM-1 on the cells, emphasizing that the adhesion of eosinophil with VCAM-1 may play a central role in the pathogenesis of asthma." (PMID 29614819, 2018). "Consequently, it was reported that IL-4/STAT-6 pathway is involved in asthma pathogenesis because STAT-6 activation lead to the differentiation of naïve T-cells into Th2 effector cells, and it regulates the production of Th2 chemokine induced by IL-4 and IL-13." (PMID 28630596, 2017).
asthma (continued). "Nevertheless, Th2 cytokines expression levels (IL-4, IL-5 and IL-13) and miRNA expression profile were similar in AR patients with and without asthma, suggesting that concomitant asthma might have a minor impact on the inflammatory profile and miRNA expression of AR patients." (PMID 27187364, 2016). "The levels of IL-4 and IL-6 and mast cell invasion were not altered in the Gpr97-/- asthmatic mice, indicating that Gpr97 might not take part in mast cell activation following IgE stimulation or cytokine production in the process of asthma induction." (PMID 26132811, 2015). "In the present study, the decrease in INF-γ, the trend toward an increase in IL-4, and the increase in the ratio of IL-4 to INF-γ after chronic ozone exposure may contribute to structural airway changes following repeated ozone exposure in a murine model of asthma." (PMID 16472404, 2006). "If a patient has severe asthma or did not benefit from ICS medications, further treatments including biological agents which act on IL-5 (mepolizumab, reslizumab), IL-4/IL-13 (dupilumab) or IgE (omalizumab) can be used." (PMID 40662069, 2025). "Human BECs from healthy and asthma donors were cultured at the air–liquid interface (ALI) and stimulated with IL-4 and IL-13, acutely or chronically, with or without IL-4Rα mAb, followed by rhinovirus (RV) infection." (PMID 40370530, 2025). "One possibility could be that, even though pro-inflammatory cytokines (IL-4, IL-13, IFNα, IFNγ, IL-17) upregulate many genes in epithelial cells (684–2,876 at 5% FDR in our analyses), they do not significantly interact with polygenic risk factors for asthma in epithelial cells." (PMID 39197446, 2024). "Using the occurrence of MP infection accompanied by asthma as the state variable (1 = asthma, 0 = non-asthma), and the value of 25-(OH)-D, IL-4, IFN-γ, and IFN-γ/IL-4 as test variables, corresponding ROC curves were plotted." (PMID 39572779, 2024). "Cases with asthma complicated by ECRS have higher serum periostin concentrations than cases with asthma without ECRS, suggesting the involvement of IL-4/IL-13 in the pathogenesis of ECRS in asthma cases." (PMID 38785953, 2024). "The genotype frequencies of ADRB2 rs1042713, IL4 rs2243250, FCER1B rs569108 and IL13 rs20541 were not significantly different between the asthma group and control group." (PMID 38049812, 2023). "Lastly, the expression levels of IL4 and IL13 were significantly higher in iNKT cells from the allergic asthma patients compared to those from healthy controls and nonallergic asthma patients." (PMID 37917548, 2023). "Probiotic and prebiotic treatments reduced the levels of Th2 cytokines (IL-4, IL-5, IL-13, IL-17, IL-25, and IL-33) and increased IFN-γ level in the BALF of asthmatic mice as compared to the non-treated asthma group." (PMID 35296330, 2022). "Interestingly, the expression of BIRC3 in GSE76262 was significantly positively correlated with inflammatory cytokines IL-4, IL-5, IL-13, and IL-25 expression (p < 0.05), which implied that BIRC3 may play an important role in the pathogenesis of inflammation in asthma." (PMID 35287655, 2022). "Other classically recognized T2 cytokines, IL‐4 and IL‐5, were not significantly elevated in the BAL of severe asthma patients compared to healthy controls." (PMID 33411348, 2021). "Moreover, RSV infection, that precedes the OVA induction of asthma, leads to significantly milder course; this could possibly be ascribed to the shift in Th1/Th2 balance among γδ T cells, namely the elevated expression of IFN-γ (Th1-like γδ T) and decreased that of IL-4 (Th2-like γδ T)." (PMID 33661375, 2021). "Since only IL-13 (but not IL-4 or IL-5) expression was diminished in Cd2−/− HDME mice, our data demonstrate a specific regulation of IL-13 by CD2 in asthma." (PMID 32477356, 2020).
asthma (continued). "Asthma endotypes are often clustered TH2 high or TH2 low, based on the presence or absence of eosinophils and IL-4, IL-5 and IL-13 cytokines in BAL, all of which we found increased following HDM challenge." (PMID 32038643, 2019). "The four loci originally discovered through GWAS on eczema (FLG, IL4/KIF3A, OVOL1 and C11orf30/LRRC32) did not reveal an effect on asthma alone." (PMID 26542096, 2015). "In contrast, Th2 cytokines (IL-4, IL-5, and IL-13) are not elevated, suggesting that AHR in this model is not Th2-mediated, contrary to AHR in asthma models." (PMID 24844383, 2014). "We did not observe a significant difference between asthma and controls with respect to the incidence of other Foxp3 or IL-10 positive cells: CD4+Foxp3+, CD4+Foxp3+CD25+, CD4+IL-10+IL-4- or CD4+Foxp3+IL-10+." (PMID 25132806, 2014). "The aim of this study was to compare the mRNA expression patterns of Interleukin (IL)-4, interferon (IFN)-γ and Acyl Co A long chain 3 (ACSL3) in peripheral blood leukocytes of children with and without asthma." (PMID 24450480, 2014). "Before the advent of genome-wide association studies (GWAS), ADAM33, ADRB2, CD14, MS4A2 (alias FCER1B), IL13, IL4, IL4R, and TNF constituted the most replicated non-HLA candidate genes with asthma and related traits." (PMID 24039878, 2013). "Treatment of established asthma with rapamycin, however, did not significantly alter the HDM-induced increases in lung mRNA levels of IL-4, IL-13 and IL-17A." (PMID 22685525, 2012). "Using flow cytometric assay of the whole blood from children with asthma, we demonstrated significantly higher frequencies of both CD4+ and CD8+T cells expressing IL-4 and IL-13 compared with blood obtained from healthy, nonatopic children." (PMID 21197090, 2010). "The IL-4 production increased again in the PBMCs from the patients with CRS-asthma, but not in patients with asthma alone, nor in other two control groups." (PMID 16677400, 2006). "After the FESS, the levels of specific IgE, IL-4 and IL-5 were attenuated significantly in CRS-asthma patients, but not in asthma alone patients." (PMID 16677400, 2006). "GM-CSF has been shown to be involved in asthma pathogenesis and in vivo can induce TH2 differentiation independent of IL-4." (PMID 15907205, 2005). "A significant decrease in the expression of the Th1 polarization factor IFN-γ and a significant increase in the expression of the Th2 polarization factors IL-4 and GATA-3 in Spp1−/−+OVA mice, which suggests a lack of OPN, increases the Th2-polarized environment in asthma." (PMID 40401951, 2025). "As for the Th2 biomarkers(IL-4 P=0.142, IL-5 P=0.4791, IL-13 P=0.6885, Serum IgE P=0.2534, TARC P=0.2074, TSLP P=0.6571), there are no significant statistical differences observed between asthma and control subjects." (PMID 40503233, 2025). "Asthmatic mice with and without fluconazole exhibited retardation of weight gain, increased IgE and IL-4 in serum, increased serum IL-6 but not serum TNF-α (increased serum IL-10 only in asthma with fluconazole), and prominent IL-4 and IgE in the lung homogenates." (PMID 39484217, 2024). "rTS‐SUCLA‐β was administered at varying dosages to mice with asthma induced by OVA, and it was showed that IFN‐γ in BALF of 50 μg rTS‐SUCLA‐β + OVA group was decreased, while IL‐4 level in the groups treated with rTS‐SUCLA‐β had no significant change compared with OVA group." (PMID 38888451, 2024). "Additionally, loratadine, when combined with montelukast, resulted in a reduction in IL-4 and TNF-α without increasing adverse effects in children with asthma." (PMID 38794179, 2024). "Thus, iNKT cells from allergic asthma patients express higher ACC1, FASN and PPARG levels and lower levels of a glycolysis, which is accompanied with higher levels of IL4 and IL13 than iNKT cells from healthy controls and nonallergic asthma patients." (PMID 37917548, 2023).
asthma (continued). "However, simple exposure to 1 μg LPS without asthma induction (LPS/PBS) did not significantly affect Foxp3, GATA3, or ROR-γt mRNA levels nor IL-10, TGF-β, IL-4, IL-5, IL-13, or IL-17 levels (p > 0.05) compared to those of Control mice." (PMID 33072079, 2020). "Migration of airway epithelial cells could be stimulated by IL-4, possibly via IRS-1/IRS-2 signaling independent of IGF-1/IGF-1R in an asthma model." (PMID 30018981, 2018). "In this study, the levels of miR-1 and the Th1-expressed cytokine IFN-γ in peripheral blood of children with acute-stage asthma were significantly lower, whereas the expression levels of the Th2 cytokines IL-4, IL-5, IL-8, and TNF-α were significantly higher than levels in children without asthma." (PMID 30046607, 2018). "In this study, we investigated the expression of IL-4, IFN-γ and ACSL3 mRNA in PBMCs of the children with and without asthma and speculated that cytokine expression in PBMCs may provide useful information regarding the allergic disease." (PMID 24450480, 2014). "It is also supported by the experimental evidence thatmucosal gene transfer of IL-12 via a vaccinia virus vector inhibited theability of lung lymphoid cells to produce IL-4 and IL-5, but not IFN-γand prevented the development of airway hyperreactivity in a mouse model ofovalbumin-induced asthma." (PMID 19381339, 2009). "Since we do not detect genotype-specific differences in mRNA degradation of IL-4 or IL-13 in polyclonally stimulated CD4+ T cells and no degradation of IL-5 mRNA, modulation of mRNA stability by KSRP does not appear to be the main reason for the effects observed in our asthma model." (PMID 40095032, 2025). "However, this bias was not seen in patients with severe asthma, in whom frequencies of IL-13–secreting TH2 cells were not significantly different from those in healthy subjects, although we did not measure frequencies of IL-4– or IL-5–secreting T cells." (PMID 25746968, 2015).